INS (insulin)
Diseases named in the same sentence as INS in open-access papers (continued):
Sharing a sentence is not in itself a finding about the gene and the disease.
diabetes (continued). "Similarly, The Diabetes Control and Complications Trial showed that poor adherence to a healthy diet was associated with poor glycemic control and increased insulin requirements in adults and youths with T1D." (PMID 37900142, 2023). "With this study, we sought to evaluate whether pharmacologic inhibition of myostatin with a myostatin inhibitory antibody (REGN647) improves muscle and bone mass, as well as muscle and bone strength, in a mouse model of insulin‐deficient diabetes." (PMID 38025035, 2023). "There are several complex causes possibly involved in the association of diabetes with breast cancer, including hyperglycemia, insulin signaling, insulin‐like growth factor 1 (IGF‐1) signaling, and regulation of endogenous sex hormones, which further increases the risk of breast cancer." (PMID 37095062, 2023). "Furthermore, diabetes is associated with considerable weight loss due to increased lipolysis and proteolysis in response to chronic hyperglycemia and defective insulin action, leading to loss of tissue protein and increased muscle atrophy." (PMID 37765360, 2023). "Altered insulin secretion dynamics are associated with worse metabolic profiles and type 2 diabetes mellitus development, thus we aimed to test whether insulin response relates to oxidative stress and inflammation in children." (PMID 37599368, 2023). "Diabetes is a chronic disease characterized by hyperglycemia, which results from a relative or absolute deficiency of insulin, the decreased sensitivity of target cells to insulin, and the glycolipid and protein metabolism disorders." (PMID 37108143, 2023). "Overall, the meta-analysis data indicate that miR-223 is significantly upregulated during GDM, which correlates well with the fact that miR-223-3p has been associated with impaired insulin sensitivity in adipose tissues and an upregulation in beta-cells during diabetes." (PMID 37047159, 2023). "Diabetes mellitus is a chronic metabolic disease caused by insufficient insulin secretion or insulin resistance, with hyperglycaemia as the typical clinical symptom, which can lead to a series of complications such as retinopathy and cardiovascular disease, and even life-threatening in severe cases." (PMID 37965892, 2023). "The two most common forms of diabetes are Type 1 Diabetes Mellitus (T1DM), characterized primarily by deficiency of insulin secretion because of autoimmune pancreatic β-cell damage, and Type 2 Diabetes Mellitus (T2DM), which occurs due to insulin resistance along with β-cell impairment." (PMID 36994279, 2023). "High levels of circulating adiponectin are associated with increased insulin sensitivity, low prevalence of diabetes, and low body mass index (BMI); however, high levels of circulating adiponectin are also associated with increased mortality in the 60–70 age group." (PMID 37768324, 2023). "Indeed, in people, FoxO genetic variants correlate with centenarians, yet impaired insulin signaling/ increased FoxO induced during adulthood causes serious clinical complications (e.g., diabetes, sarcopenia)." (PMID 37523525, 2023). "Diabetes is regarded as the most critical and chronic medical condition that is illustrated by the increased blood glucose levels in association with impaired insulin activity due to the defective pancreatic beta cells (β-cell) function." (PMID 37928539, 2023). "Diabetes mellitus (DM) is a chronic metabolic disease characterized by high blood glucose levels caused by insulin resistance in peripheral tissues or insufficient pancreatic insulin secretion." (PMID 37904700, 2023). "Although insulin is a highly effective therapy for diabetes, the use of exogenous insulin is been associated with a number of side effects, including weight gain, a worsening of diabetic retinopathy, changes in the refractive properties of the lens, dizziness, and difficulty breathing." (PMID 37089422, 2023).
diabetes (continued). "Type 1 diabetes mellitus (Type 1DM) is the most common type of diabetes in children with about 90% prevalence and is caused by a decrease or loss of production of insulin as a result of autoimmune destruction of the β pancreatic cells in the islets of Langerhans." (PMID 37185051, 2023). "CFRD—a distinctive variant of diabetes, is characterized by a subtle and gradual onset that may be heralded by an extended period of progressive insulin inadequacy." (PMID 38136081, 2023). "Diabetes secondary to pancreatic disease (post-pancreatitis diabetes, or a form of type “3c” diabetes) results primarily from structural and functional loss of glucose-normalizing insulin production and is frequently either misdiagnosed as type 2 diabetes or underdiagnosed." (PMID 38264059, 2023). "Mid-to-high-frequency noise exposure has an adverse effect on insulin control and leads to a rise in blood sugar, which may cause type 2 diabetes mellitus between 1,000 and 2,000 Hz." (PMID 36778576, 2023). "Individuals may suffer from different types of diabetes, such as type‐1 diabetes caused by insufficient insulin production or type‐2 diabetes (inability to use insulin properly), or both (which occur with several forms of diabetes)." (PMID 37823149, 2023). "Precision medicine in monogenic diabetes involves the customization of treatment strategies based on specific genetic mutations that impact the functioning of beta cells and the production of insulin." (PMID 37724233, 2023). "This is similar to results observed in adults at risk for diabetes in the Diabetes Prevention Program, where a high β-cell pPS was associated with an increased risk of diabetes and worsening in insulin secretion despite interventions with intensive lifestyle and metformin." (PMID 38590442, 2023). "Therefore, a deficiency of insulin or the insensitivity of its receptors plays a central role in all forms of diabetes mellitus." (PMID 37569372, 2023). "The problem of diabetes in children poses significant public health implications due to the serious complications it can cause in later life as a result of either chronic insufficient insulin secretion or impaired insulin action in later years." (PMID 36835954, 2023). "Additionally, the inhibition of miR-29 improves insulitis, insulin resistance, and dysfunction of glucose-stimulates insulin secretion, causing the attenuation of inflammation and diabetes." (PMID 36896239, 2023). "The epidemiologic associations of diabetes and obesity with HFpEF in women might suggest that insulin resistance and resistance to insulin’s microvascular effects may contribute to the sex differences in HF." (PMID 37658327, 2023). "In summary, differential expression of urinary insulin signaling pathway related proteins may be associated with diabetes." (PMID 36749274, 2023). "While the treatment requirements of type 1 diabetes appear to be principally mediated through development of severe insulin deficiency, which is measurable using C-peptide, insulin secretion can be maintained at type 1 diabetes diagnosis and levels overlap with other diabetes types." (PMID 37728732, 2023). "This bias leads to suboptimal diabetes management, causing frequent hyper and hypoglycemia, a dysregulation of glycated hemoglobin, blood glucose out of control, and consequent needs to often intervene with extra insulin or carbohydrates." (PMID 37402564, 2023). "Also, studies have found that vitamin D supplementation improved beta cell function and insulin sensitivity, especially in those at high risk for diabetes." (PMID 37895163, 2023). "We found that participants in the IR group were more likely to be obese and to have higher LDL, triglycerides, fasting glucose, insulin, TyG index and TyG-BMI index, as well as higher risk of hypertension, diabetes and female infertility compared to the other group (P < 0.05)." (PMID 37828472, 2023).
diabetes (continued). "This may reflect the beneficial effects of vegetables and fruits intake since it is known that vegetable and fruits contain antioxidants that may reduce insulin resistance and β-cells apoptosis thus reducing the risk of diabetes." (PMID 37266136, 2023). "Taken together, these results support the hypothesis that myostatin inhibition could prevent muscle atrophy in a condition of insulin‐deficient diabetes." (PMID 38025035, 2023). "However, it should be clearly underlined that altered microRNAs in diabetes affect many processes connected with cancer development, such as insulin resistance/insulin signaling dysregulation, inflammation, and oxidative stress." (PMID 37373398, 2023). "This may be because vitamin D deficiency impairs insulin synthesis and insulin sensitivity, thus creating a predisposition to develop diabetes." (PMID 37959300, 2023). "Moreover, a lower C16:0/C18:1 ratio is beneficial and improves insulin sensitivity, since it protects against risk of developing diabetes in humans." (PMID 37857341, 2023). "Diabetes is associated with abnormal secretion and/or action of insulin in the body." (PMID 37298479, 2023). "However, in diabetes, glucose homeostasis is disrupted by the underlying pathophysiology and often by pharmacological agents designed to enhance or supplement insulin secretion." (PMID 37630716, 2023). "Whilst it is unknown what the triggering factors causing diabetes are, it is known that autoreactive effector T cells kill the beta cells that produce insulin in the islets of Langerhans6." (PMID 37210405, 2023). "Failure of insulin signaling causes tau protein hyperphosphorylation, in addition to increased neurotoxic Aβ deposition at specific levels of hyperinsulinemia, all of which can lead to decreased cognitive function in diabetes." (PMID 37077347, 2023). "Previous meta-analysis studies have reported that having diabetes is associated with a 20–30% increased mortality risk among cancer patients under insulin therapy with long diabetes duration, which was more apparent among liver, breast, endometrial, and colorectal cancer patients." (PMID 37510134, 2023). "In addition, insulin treatment is associated with significant emotional distress in individuals with diabetes and their families." (PMID 37293006, 2023). "Diabetes is a chronic disease caused by the pancreas’ inability to produce or properly use insulin." (PMID 38005726, 2023). "Patients with diabetes who are treated with insulin have a 25% higher risk of infection." (PMID 37046886, 2023). "Type 2 diabetes mellitus (T2DM) has a variety of causes that lead to insufficient insulin secretion or the inability of the body to effectively use insulin, resulting in a sustained increase in blood sugar levels and impaired carbohydrate, lipid, and protein metabolism." (PMID 38115042, 2023). "Proinflammatory cytokines such as tumor-necrosis factor α (TNF-α) and interleukin-6 (IL-6) not only involved in the pathogenesis of hypertension, but also interfered with the insulin signaling pathways which were associated with insulin resistance and diabetes mellitus." (PMID 37139334, 2023). "In addition, the more muscle mass involved in glucose uptake, the better insulin resistance and the lower risk of prediabetes or overt diabetes." (PMID 37792730, 2023). "Furthermore, we observed remission of diabetes in two patients with heterozygous pathogenic INS variants (in one case for more than 1 year)." (PMID 36398453, 2023). "The current study showed that a fifth of the studied population was depressed with male patients being at a higher risk of developing depression while being Qatari and treatment of diabetes with insulin were associated with a lower risk for developing comorbid depression in people with diabetes." (PMID 39035064, 2023). "Besides the increase in the subsequent risk of diabetes, we found a clear relationship between increased requirement of insulin treatment in cancer survivors." (PMID 36831436, 2023).
diabetes (continued). "Insulin gene mutations can cause the development of unique diabetes subtypes." (PMID 37048081, 2023). "One possible reason for this is that patients with diabetes may have various factors associated with muscle protein degradation including insulin resistance and activation of autophagy." (PMID 36904122, 2023). "There is, however, room to improve outcomes, but one-third lost >10% body weight and the mechanism underpinning a 43% diabetes remission rate appears the same as in white Europeans, involving loss of excess ectopic body-fat and resultant improved insulin sensitivity." (PMID 36777452, 2023). "Additionally, chronic disease (e.g., diabetes mellitus) can cause increased loss of muscle mass and strength because of insulin resistance, which causes reduced protein synthesis and increased protein degradation." (PMID 37046939, 2023). "Additionally, we wanted to eliminate the effect of diseases other than cancer on the analysis of the risk of incident development for type 2 diabetes, requirement of insulin, and diabetes-associated complication events." (PMID 36831436, 2023). "Diabetes mellitus is a disease of carbohydrate, protein and fat metabolism impairment causing hyperglycemia and, therefore, there is a shortage or reduced effectiveness of endogenous insulin." (PMID 36671049, 2023). "Insulin-positive (+) cells (IPCs), detected in multiple organs, are of great interest as a probable alternative to ameliorate pancreatic beta-cells dysfunction and insulin deficiency in diabetes." (PMID 38019818, 2023). "Diabetes mellitus is a disorder of carbohydrate metabolism caused by the hypo-production of insulin in pancreatic β-cells and/or insufficient insulin action in carbohydrate metabolism–competent organs such as the liver, skeletal muscle, and white adipose tissue." (PMID 36834633, 2023). "Type 2 diabetes mellitus (T2D) is a chronic metabolic disease, mainly characterized by an increased blood glucose concentration produced by deficient insulin secretion by pancreatic islet β cells in the context of impaired insulin sensitivity." (PMID 37111688, 2023). "Notably, C1 and C5 characterized by the expression of RBP4 and FFAR4, which are diabetes-associated genes and correlate with INS resistance, are found to be increased in T2D and obese individuals." (PMID 37270452, 2023). "In addition, diabetes mellitus can be associated with congenitally low insulin secretion and is commonly caused by insulin resistance due to genetic/environmental factors." (PMID 37111730, 2023). "Furthermore, 64.6% correctly identified variables associated with diabetes, and 81.0% recognized low blood glucose reactions resulting from taking rapid-acting insulin." (PMID 37388615, 2023). "Human pluripotent stem cells (hPSCs) can generate insulin-producing beta cells for diabetes treatment, but residual undifferentiated cells may cause tumors." (PMID 37777562, 2023). "Diabetes is caused by an absolute or relative deficiency of insulin secretion." (PMID 36843576, 2023). "Diabetes mellitus (DM), a common human health problem around the globe, is a metabolic disorder and it is characterized by high levels of blood sugar (hyperglycemia), causing dysfunction in insulin secretion and/or sensitivity." (PMID 38202704, 2023). "While this review focuses on SST-dependent mechanisms of glucagon counterregulatory failure in insulin-deficient diabetes, other causative mechanisms, such as changes in the anatomical and paracrine relationships between α- and β-cells, may also play a role." (PMID 38298268, 2023). "On the other hand, there is a controversy over the use of insulin for patients with diabetes at risk of cancer, as it mediates not only the glucose-lowering but the cell proliferative effect of insulin receptor signaling, thus possibly leading to the outgrowth of latent tumor buds." (PMID 37852976, 2023).
diabetes (continued). "Diabetes is a disease affecting millions of people worldwide and is characterized by chronic hyperglycemia caused by defects in insulin production or insulin resistance in the peripheral tissues, leading to long-term complications including ulcers, retinopathy and neuropathy." (PMID 36839820, 2023). "Diabetes is a chronic metabolic disorder of the endocrine system characterized by persistent hyperglycemia appears due to the deficiency or ineffective use of insulin." (PMID 37764399, 2023). "Long duration of diabetes and long-term insulin use are negatively associated with HU." (PMID 37964960, 2023). "Diabetes mellitus is a group of metabolic disorder diseases caused by absolute or relative insulin secretion insufficiency and (or) insulin utilization obstacles, with hyperglycemia as the main feature, causing a longer-term health aftermath, higher mortality risks, and reduced life expectancy." (PMID 37664859, 2023). "Renal clinic attenders with T2DM, particularly if insulin-treated, remained at increased risk of diabetes-related complications, including severe hypoglycaemia, with limited input from the colocated hospital diabetes team." (PMID 37152098, 2023). "Although further studies are required, these findings suggest that it may be important to weigh the potential harms of insulin among patients with diabetes who are at high risk of liver or pancreatic cancers due to family history or other risk factors." (PMID 37481610, 2023). "Furthermore, the frequency of self-monitoring of blood glucose, food, duration of diabetes, frequency of clinic visits, use of an insulin regimen, and family engagement in diabetes-related activities are linked to the patient's level of glycemic control." (PMID 37759193, 2023). "Studies have reported that tacrolimus can reduce insulin secretion and insulin receptor expression by inducing pancreatic cell apoptosis, thereby increasing insulin resistance and plasma glucose concentrations to cause diabetes." (PMID 36843576, 2023). "Investigate the effects of folate supplementation on the outcome of insulin resistance and diabetes, evaluating the effect of placebo-controlled folate supplementation, alone or in combination with other B vitamins, on fasting glucose, insulin, HOMA-IR, HbA1c, or risk of type 2 diabetes." (PMID 38068801, 2023). "In addition, in the T2DM-SCH+ group, due to the existence of insulin resistance, insulin compensatory functions increase, and failure to compensate will lead to an increased risk of diabetes." (PMID 37484968, 2023). "Therefore, in this study, for the first time, the effect of diabetes drugs metformin, sulfonylureas, and insulin on the risk of hip fracture was investigated in a meta-analysis." (PMID 37161384, 2023). "Diabetes mellitus manifests in various forms including Type I and Type II diabetes mellitus, as well as other genetic dysfunction of beta-cell function or insulin action inefficiency." (PMID 38020229, 2023). "However, in our study, we compared the use of insulin pens versus insulin pumps and found that patients treated with insulin pens were significantly at higher risk for developing diabetes distress in comparison to those using insulin pumps." (PMID 37193469, 2023). "The vitamin improves the body’s response to insulin, which improves blood glucose levels, and acts as a potent antioxidant that safeguards cells from damage caused by oxidative stress, thereby reducing the likelihood of diabetes and its related complications." (PMID 37764713, 2023). "The high abundance of Ruminococcus may be related to the imbalance in intestinal microecology in patients with diabetes and may lead to damage to the intestinal mucosal barrier, thus affecting insulin sensitivity and increasing the risk of diabetes." (PMID 37893758, 2023). "Further, the small proportion of the insulin-deficient subgroup may result from the presence of ketosis-prone diabetes, possibly hidden within the age-related cluster." (PMID 37402743, 2023).